RNU6-782P (RNA, U6 small nuclear 782, pseudogene)
Gene: Small nuclear RNA gene on chromosome 19 (15,145,215 to 15,145,318, forward strand). Ensembl gene ENSG00000252661.
Homologues: Orthologues: chimpanzee U6 (99% identical). Paralogues in human: RNU6-310P (82% identical), RNU6-1175P (81% identical), RNU6-1209P (81% identical), RNU6-183P (81% identical), RNU6-689P (81% identical), RNU6-797P (81% identical), RNU6-1094P (80% identical), RNU6-1145P (80% identical), RNU6-116P (80% identical), RNU6-11P (80% identical), RNU6-1243P (80% identical), RNU6-1316P (80% identical), and 1287 more.